MGMT (O-6-methylguanine-DNA methyltransferase)
Diseases named in the same sentence as MGMT in open-access papers (continued):
Sharing a sentence is not in itself a finding about the gene and the disease.
colon carcinoma (continued). "The median methylation levels of MLH1, MGMT, p16INK4a/+68, and p16INK4a/+235 in matching mucosa of colon cancer patients (non-cancerous mucosa) were 1.2% (range 0.6–6.2), 3.0% (range 0.6–10.4), 2.8% (range 1.2–23.6), and 3.6% (range 1.9–7.6), respectively." (PMID 40357388, 2025). "Similarly, overexpression or targeted knockdown of β-catenin lead to an increase or decrease, respectively, of the MGMT promoter in SK-N-AS neuroblastoma, DAOY medulloblastoma, SW480 and LS174T colon carcinoma cells." (PMID 26603103, 2015). "Furthermore, low level methylation of MGMT has been reported in normal appearing colon mucosa in patients with a correspondingly MGMT methylated tumor, as well as individuals without colon cancer." (PMID 24151575, 2013). "This study compared MLH1, MGMT, p16INK4a, and LINE-1 methylation with gene expression in colon tumors, matched non-cancerous mucosa, and control mucosa to identify signs of premalignancy." (PMID 40357388, 2025). "The aim of study was to quantify and compare the methylation levels of MLH1, MGMT, p16INK4a, and LINE-1, and the gene expression levels of MLH1, MGMT, and p16INK4a in colon tumors, matched non-cancerous mucosa and control mucosa to identify early signs of putatively premalignant changes." (PMID 40357388, 2025). "The combination of low tumor MGMT expression and nuclear DDR biomarker induction did not correlate with clinical response in this small test group—2 of 3 MGMTlow/DDR+ patients progressed within the first 2 cycles of treatment (patients 50 and 51, both patients with colon cancer)." (PMID 33216844, 2020).
adenoma (27 papers, 2006 to 2025). A neoplasm arising from the epithelium. "We also derived the optimal cutoff of MGMT h-score in the adenoma specimen as being significantly associated with the response to TMZ." (PMID 34975752, 2021). "Although the serrated pathway allows such a transition, only a small proportion of hyperplastic lesions transform to dysplastic serrated adenomas after acquiring other gene mutations, such as hMLH1 or MGMT." (PMID 18159236, 2007). "Similarly, low-level MGMT is also associated with a better prognosis in TMZ-treated adenoma patients." (PMID 26400193, 2015). "In accordance with our result, a further study showed that MGMT methylation was progressively increased during the normal–adenoma–carcinoma evolution." (PMID 37510370, 2023). "We observed an unmethylated MGMT promoter in all adenoma tissue samples immediately after the operation (1.52–6.12%)." (PMID 29344904, 2018). "Nevertheless there is an earlier study on plasma methylation of RASSF2A, APC, MGMT and Wif-1 that suggested a more promising biomarker panel for adenoma with sensitivity of 86.5% and specificity of 92.1%." (PMID 29765549, 2018). "In the first 12 h after adenoma removal, tissue samples remained MGMT positive in significantly more samples when fixated with formaldehyde than with RCL2, respectively (96 vs. 81%, p = 0.025)." (PMID 29344904, 2018). "Although small case series evaluated the MGMT status prior to TMZ treatment in aggressive adenomas and pituitary carcinomas, a systematic evaluation of MGMT and MSH6 status in functioning pituitary macroadenomas has not been performed thus far." (PMID 28900805, 2017). "Hypermethylation of genes involved in cell cycle regulation (CDKN2A/p16/MTSI) and repair of mutagenic DNA lesions (MGMT) contributes to formation of adenomatous polyps and progression through the adenoma–carcinoma sequence." (PMID 29259973, 2017). "MGMT immunoexpression was assessed in a group of 45 SPAs of various histological subtypes, and the degree of expression (low expression defined as ≤50% immunostained adenoma cells and high as >50%) correlated with tumor aggressiveness." (PMID 30020466, 2019). "Furthermore, adenomas with low-to-moderate MGMT immunoexpression were significantly more often recurrent (76 vs. 30%, p < 0.001) and invasive (64 vs. 28%, p = 0.002)." (PMID 28900805, 2017). "Low MGMT expression (<25 %) was found in 57 % of carcinomas and 60 % of invasive adenomas." (PMID 26400193, 2015). "However, it may be reasonable to attempt a 3-month rechallenge in patients with late relapse and low MGMT, as a report of 9 adenomas treated with a second course of TMZ showed that late relapse after the first course was associated with improved response." (PMID 34867776, 2021). "However, no apparent relationship between MGMT expression and age was observed in patients with Cushing disease or GH adenomas, which might be because of the various mechanisms of MGMT expression in different adenoma subtypes." (PMID 26400193, 2015). "However, among TAs < 10 mm, KRAS mutation occurred in 3/25 (12%) adenomas with no MGMT loss but in 4/8 (50%) adenomas with MGMT loss (P < 0.04)." (PMID 16879389, 2006). "ADAMTS1, CDKN2A, CRABP1, MLH1, NR3C1, RUNX3, and SCGB3A1 showed increasing methylation frequencies from adenomas to carcinomas, while HOXA9, MAL, and MGMT displayed overall equal methylation frequencies in all tumor subgroups." (PMID 19117505, 2008).
adenoma (continued). "Although sample sizes gradually increased, later studies—including analyses of MGMT promoter methylation—did not establish this marker as predictive of temozolomide response in aggressive adenomas." (PMID 39859246, 2025). "Lower response of NFPAs to TMZ than functioning adenomas is not explained by differential MGMT expression, as low MGMT has been noted with almost similar frequency in both functional and non-functional tumors." (PMID 34975752, 2021). "We applied the same criteria to the adenoma samples in our present series and revealed no statistical significant difference compared to MGMT positive IHC tissue samples." (PMID 29344904, 2018). "In addition, MGMT promoter methylation tended to be more common in the aggressive pituitary adenomas, with 33 % in pituitary carcinomas, 42 % in SS3 adenomas, and 43 % in aggressive pituitary adenoma." (PMID 26400193, 2015). "Likewise, the MGMT promoter methylation did not appear to be a reliable prognostic marker for responses to temozolomide in aggressive adenomas." (PMID 39859246, 2025). "Additionally, MGMT immunoreactivity was evaluated in 23 silent subtype 3 adenomas; 78% showed no MGMT immunoreactivity, 17% displayed immunoreactivity in <25% of the tumor cells, and none of the tumors showed high immunoreactivity (>50%)." (PMID 30020466, 2019). "The MGMT, CDKN2A, and MLH-1 genes were methylated in 48%, 31%, and 0% of adenomas and 16%, 27%, and 10% of those with no detectable pathologies." (PMID 22969796, 2012).
lymphoma (22 papers, 2007 to 2025). A malignant (clonal) proliferation of B- lymphocytes or T- lymphocytes which involves the lymph nodes, bone marrow and/or extranodal sites. "On the other hand, a correlation between MGMT and resistance to the alkylating agent CCNU as well as an increased sensitivity to this drug in canine lymphoma cells cultured with a MGMT inhibitor has been reported." (PMID 34477324, 2021). "The canine lymphoma cell line 17–71 showed low MGMT mRNA expression and enzyme activity (about 90 fmols/mg protein)." (PMID 29061931, 2015). "The potential role of MGMT in lymphoma stems from the fact that MGMT inactivation favors lymphomagenesis in knockout mice." (PMID 21416004, 2009). "This suggests that MGMT-mediated in vivo selection of anti-HIV gene-modified cells should be well tolerated, and HIV patients who suffer from HIV-associated lymphoma in particular could benefit from this approach." (PMID 19888329, 2009). "Therefore, considering that these heritable alterations could be maintained also after the loss of the virus, we investigated the methylation pattern of the CDH1 and MGMT gene promoters in whole lymphoma tissue sections." (PMID 32483241, 2020). "Additionally, the MGMT selection strategy should be particularly effective for patients with AIDS lymphoma who will require an HSC transplant and may also be treated with the chemotherapy agent, BCNU which could increase marking of the MGMTP140K anti-HIV vector." (PMID 19888329, 2009). "One study tested canine lymphoma cells for MGMT methylation status and could not report a significant relation to MGMT activity." (PMID 34477324, 2021).
prostate carcinoma (22 papers, 2011 to 2025). A carcinoma that arises from epithelial cells of the prostate gland. "Except for one protective variant (MTHFR rs1801133) for prostate cancer (OR = 0.684, 95% c.i.=0.565–0.828), six of the seven variant (in MGMT, XRCC1, OGG1, ERCC2 and CASC8) showed risks for prostate cancer." (PMID 26967244, 2016). "However, a higher risk of prostate cancer was observed with higher intake of alcohol among the O6-Methylguanine-DNA methyltransferase (MGMT) gene Ile143Val polymorphism carriers of the variant genotype in comparison with the MGMT Ile143Ile common genotype with lower alcohol intake." (PMID 34684583, 2021). "In one study the development of prostate carcinoma was correlated with the methylation pattern of MGMT." (PMID 22191037, 2011). "Genistein also induced promoter hypomethylation and reactivated the expression of tumor suppressor genes GSTP1, EPHB2, p21, RARβ, p16INK4a, and MGMT in breast cancer, kidney cancer, esophageal squamous cell carcinoma, and prostate cancer cell lines, leading to cell cycle arrest and cell death." (PMID 32878338, 2020). "For example, adenomatous polyposis coli (APC) promoter methylation could be a biomarker for early diagnosis of prostate cancer, and O6-methylguanine-DNA-methyltransferase (MGMT) promoter methylation might be a predictive biomarker for cancer prognosis." (PMID 31590287, 2019). "The brains of young adult MGMT-deficient mice given a single dose of MAM show DNA lesion-linked changes in cell-signaling pathways associated with miRNA-1, which is implicated in colon, liver, and prostate cancers, and in neurological disease, notably AD." (PMID 23060898, 2012). "MGMT hypermethylation plays an important role in development of prostate carcinoma." (PMID 22191037, 2011). "We also demonstrate the statistically significant down-regulation of DNA methyltransferases (COMT, MGMT, EHMT2, and SIRT1 deacetylase) in saffron-treated prostate cancer cells." (PMID 38201944, 2023). "GE can reverse DNA hypermethylation and reactivates p16INK4a, RARb and MGMT in KYSE 510 esophageal squamous cell carcinoma cells, KYSE 150 cells, prostate cancer LNCaP and PC3 cells." (PMID 31030484, 2019). "Multiple genes, such as GSTP1, APC, MDR1, MGMT, and RASSF1A, show higher methylation frequency in prostate cancer samples compared to BPH and non-neoplastic prostate samples." (PMID 37234978, 2023).
anaplastic astrocytoma (20 papers, 2010 to 2025). "The continuous dose-dense Tmz for recurrent anaplastic astrocytoma can help overcome the drug resistance by decreasing MGMT activity with anti-angiogenic properties." (PMID 33671796, 2021). "We scheduled the patient for a biopsy of the lesion, which revealed an anaplastic astrocytoma (IDH-mutation, MGMT+, WHO grade III)." (PMID 32733798, 2020). "Note that, in a recent multicenter series of 102 histologically defined “anaplastic astrocytomas with piloid features”, MGMT promoter methylation was observed in 45% of tumors." (PMID 31362435, 2019). "Patient 4 was a 57 year-old man whose original tumor was an IDH1/2 wild type anaplastic astrocytoma with unmethylated MGMT promoter and PTEN deletion." (PMID 29113409, 2017). "Hence, anaplastic astrocytoma with IDH1 wild-type and MGMT methylation patients may be more suitable treated with chemotherapy and if the MGMT is unmethylated, they are better treated by radiotherapy only." (PMID 33671796, 2021). "Patient 3 was a 26-year old female patient (aA_8) diagnosed with anaplastic astrocytoma, IDH wildtype (WHO grade III) without MGMT promoter methylation." (PMID 32758285, 2020).
non-small cell lung carcinoma (19 papers, 2012 to 2026). A group of at least three distinct histological types of lung cancer, including non-small cell squamous cell carcinoma, adenocarcinoma, and large cell carcinoma. "In this study, we demonstrated TMZ–POH inhibited MGMT dependent on proteasomal pathway and this inhibition is a significant factor in its toxic effect in the non-small cell lung cancer (NSCLC) cells." (PMID 29426908, 2018). "In conclusion, we identified significant associations between seven genes (CDKN2A, RASSF1, MGMT, RARB, DAPK, WIF1 and FHIT) and smoking behavior in non-small cell lung cancer patients." (PMID 25754026, 2015). "Cranial radiation (2 Gy) followed by AMONs (intravenous, 10.5 mg/kg) reduced MGMT expression by 50% in both orthotopic cerebellar D283 medulloblastoma and intracerebral H460 non-small cell lung carcinoma (NSCLC) xenograft models." (PMID 33850305, 2022).
brain cancer (18 papers, 2011 to 2026). A primary or metastatic malignant neoplasm affecting the brain. "Out of all molecular signaling responsible for brain tumors, IDH and MGMT are the most common genes whose mutation causes brain cancer; hence, the prediction of the mutation status of these genes is more important for better prognosis." (PMID 36011048, 2022). "Previous studies suggested that the rs16906252 T allele is associated with methylated promoter in MGMT in lung, colorectal, and brain cancer." (PMID 28575062, 2017). "These strategies can now be validated and optimised in prospective clinical studies, and can be extended to identify other important molecular alterations, such as ATRX loss, 1p/19q co-deletion and/or MGMT hypermethylation, with which brain cancer type can be stratified pre-operatively." (PMID 33302429, 2020). "Both, MGMT promoter methylation and IDH1 mutations are associated with a better overall survival of patients with primary brain cancers." (PMID 38835368, 2024). "The MGMT status in brain cancers is of huge importance for treatment because the antimutagenic function of MGMT interferes with the cytotoxic actions of anticancer alkylating agents." (PMID 33801310, 2021). "Human MGMT remains a critical DNA repair gene at the crossroads of carcinogenesis, malignant progression, and anticancer therapies, particularly for brain cancers." (PMID 34201219, 2021). "For example, brain cancers that lose activity of the O-6-methylguanine-DNA methyltransferase (MGMT) enzyme, which can directly reverse O-6 adducts, are more sensitive to the DNA-methylating drug temozolomide (TMZ)." (PMID 33788831, 2021). "Due to the small number of samples, further validation on a larger cohort of Han-Chinese and east Asians will shed light on more robust conclusions of the clinical utility or MGMT genetic testing for brain cancers." (PMID 28575062, 2017). "This study aims to investigate the rs16906252 polymorphisms in Han-Chinese and evaluate the clinical relevance of the rs16906252 genotype, the MGMT promoter methylation in the brain cancer patients." (PMID 28575062, 2017). "Overexpression of MGMT is a well-established resistance mechanism against these alkylating drugs in different brain cancers." (PMID 28346397, 2017). "O-6-methylguanine-DNA methyltransferase (MGMT) is a critical brain cancer biomarker." (PMID 39944136, 2025). "The response of various TMZ-resistant brain cancer cells could be attributed to the overexpression of a gene named O6-methylguanine methyltransferase (MGMT)." (PMID 35804888, 2022). "O6-Methylguanine-DNA-methyltransferase (MGMT) is a simple, low molecular weight (~23 kDa), antimutagenic DNA repair protein expressed in varying amounts in normal tissues, but generally, at elevated levels in human malignancies including brain cancers." (PMID 34201219, 2021). "Most IDH1 mutant brain cancers fail to express MGMT protein, largely due to promoter methylation, which may explain better therapeutic responses in patients positive for IDH1 mutations." (PMID 28346397, 2017). "Various biomarkers relevant for GBM (IDH1, MGMT, GFAP, hTERT) are detectable in ctDNA from brain cancer patients, suggesting that the BBB does not effectively prevent its release into the blood." (PMID 32650387, 2020).